RNF32 (ring finger protein 32)
Description:
May play a role in sperm formation.
Synonyms: FKSG33; HSD15; LMBR2
Tractability: No criterion of Open Targets' tractability assessment is met for any kind of drug.
Gene: Protein-coding gene on chromosome 7 (156,640,281 to 156,677,191, forward strand). Ensembl gene ENSG00000105982.
Subcellular location: Cytoplasm
Subcellular location (Human Protein Atlas): Cytosol; Nuclear bodies
Gene Ontology:
Molecular function: protein binding
Cellular component: aggresome; cytosol; endosome; cytoplasm
Genetic constraint (gnomAD): Loss-of-function variants: 33 observed, 36.94 expected, observed/expected ratio (o/e) 0.89, 90% interval 0.68 to 1.2. The upper end of that interval is the gene's LOEUF score, 1.2, which puts it in group 5 of 6, group 1 being the genes least tolerant of losing a copy. Missense variants: 395 observed, 439.49 expected, observed/expected ratio (o/e) 0.9, 90% interval 0.83 to 0.98. Synonymous variants: 148 observed, 164.01 expected, observed/expected ratio (o/e) 0.9, 90% interval 0.79 to 1.03.
Homologues: Orthologues: chimpanzee RNF32 (99% identical), rabbit RNF32 (83% identical), dog RNF32 (82% identical), mouse Rnf32 (78% identical), rat Rnf32 (78% identical), guinea pig RNF32 (73% identical), macaque RNF32 (67% identical), tropical clawed frog rnf32 (57% identical), zebrafish rnf32 (45% identical).
Diseases named in the same sentence as RNF32 in open-access papers:
RNF32 is named in the same sentence as 11 diseases in open-access papers, as found by Europe PMC text mining. Sharing a sentence is not in itself a finding about the gene and the disease. The quoted sentences say what the papers report.
colon cancer (1 paper, 2024). "The expression profile of RNF32 was significantly elevated in different colon cancer cell lines when compared to that of normal intestinal epithelial NCHM460 cells." (PMID 38270646, 2024). "Moreover, we investigated the effects of knockdown and overexpression of RNF32 expression in colon cancer cell lines (Caco2 and SW480)." (PMID 38270646, 2024). "However, given the scarcity of research regarding RNF32’s involvement in colon cancer, our findings offer valuable insight into the potential of RNF32 as a novel therapeutic target for COAD patients." (PMID 38270646, 2024). "Our subsequent experimental investigations revealed that RNF32 is significantly overexpressed in colon cancer cells, RNF32 may promote the proliferation, migration, and invasion of colon cancer cells by inhibiting apoptosis." (PMID 38270646, 2024). "Thus, RNF32 may promote the proliferation, migration and invasion of colon cancer cells by inhibiting apoptosis." (PMID 38270646, 2024). "The cell vitro experiments showed that the expression level of RNF32 was upregulated in colon cancer cell lines compared with normal cell lines." (PMID 38270646, 2024).
depression (1 paper, 2024). "Additionally, there exist a multitude of significant genes that vary between sexes and are linked to depression, like ORM1, ORM2, RNF32, SLC25A5, Thbs1, and Cadps2 etc., manifesting sex-specific impacts on depression risk." (PMID 38903903, 2024).
Infertility (1 paper, 2025). "Importantly, this study precludes RNF32 as a viable contraceptive target or monogenic infertility factor, thereby optimizing research resource allocation by eliminating nonproductive investigative pathways." (PMID 40755799, 2025).
polydactyly (1 paper, 2016). A disease characterized by the presence of polydactyly, including syndromic and non-syndromic forms. "We speculate that the SNPs close to or in RNF32 may be critical for regulating the temporal and spatial expression of SHH, which contributes to polydactyly in Houdans." (PMID 26859147, 2016).
cancer (3 papers, 2021 to 2025). A tumor composed of atypical neoplastic, often pleomorphic cells that invade other tissues. "Moreover, SPP1+ macrophages interact with tumor cell CD44, synergizing with RNF32 to enhance cancer stemness via Wnt signaling." (PMID 41387204, 2025). "Moreover, we found that RNF32 may promote the proliferation, migration and invasion of cancer cells in vitro by inhibiting apoptosis." (PMID 38270646, 2024).
tumor (1 paper, 2025). "This study establishes RNF32 as a dual-functional driver of metastasis and proposes IAA as a promising therapeutic agent, offering new hope for targeting both tumor-intrinsic EMT and the immune microenvironment in CRC liver metastasis." (PMID 41387204, 2025). "Functional assays demonstrate that RNF32 promotes tumor cell proliferation, invasion, and epithelial-mesenchymal transition (EMT) in vitro, and drives tumor growth and liver metastasis in vivo." (PMID 41387204, 2025).
RNF32 also shares sentences with these, for which no sentence is quoted: Barrett esophagus (1 paper); Behcet’s syndrome (1); colorectal cancer (1); esophageal cancer (1); Liver (1).